CGAS (cyclic GMP-AMP synthase)
Diseases named in the same sentence as CGAS in open-access papers (continued):
Sharing a sentence is not in itself a finding about the gene and the disease.
cancer (continued). "Overall, we provide evidence that mechanical force‐induced cGAS‐STING pathway activation in carcinoma cell facilitates VHPV liver metastasis by recruitment of splenic monocytes/macrophages into liver metastatic niche." (PMID 39737867, 2025). "As expected, the chemotactic migration of Raw264.7 cells by mechanical compressed carcinoma cells was impaired by cGAS inhibitor." (PMID 39737867, 2025). "By analyzing migration using conditioned media, it was demonstrated that cGAS inhibitor treatment blocked chemokine expression in compressed carcinoma cells, ultimately blocking macrophage migration." (PMID 39737867, 2025). "We conclude that mechanical force induces cGAS activation in carcinoma cell to recruit monocytes/macrophages to facilitate liver metastasis." (PMID 39737867, 2025). "Taken together, these data suggest that cGAS activation in carcinoma cells and supplementation of splenic monocytes/macrophages to the liver are both essential for exacerbating liver metastasis." (PMID 39737867, 2025). "In this study, we report that in the VHPV liver metastasis, carcinoma cells pass through the narrow capillaries leading to mechanical force‐induced nuclear deformation and cGAS activation." (PMID 39737867, 2025). "Taken together, these data provide evidence for cGAS enzyme activity inhibition in carcinoma cells attenuate inflammatory cell infiltration and thus ameliorates liver metastasis." (PMID 39737867, 2025). "In this study, we showed that cGAS-dependent dsDNA sensing by cancer cells is critical for the effects of T cell priming." (PMID 38413714, 2024). "Based on this premise, Cen and colleagues developed ZnS@BSA nanoclusters to generate H2S under acidic conditions, which led to ROS accumulation in cancer cells and subsequent mitochondrial damage and DNA release, thus activating cGAS/STING signals." (PMID 39310098, 2024). "In recent years, the cyclic GMP-AMP synthase (cGAS)-stimulator of interferon genes (STING) signaling pathway has emerged as a crucial player in cancer immunity." (PMID 38185685, 2024). "Relationship and current development of the cGAS-STING pathway to individual cancer therapy method will be discussed in the following sections." (PMID 39125107, 2024). "Given that cGAS-STING signaling is intricately connected with autophagy, the following section will provide insights into how autophagy affects cGAS-STING signaling in the context of cancer." (PMID 38660307, 2024). "While it was previously assumed that TH1902 acted directly on cancer cells to induce cell death, our current study highlights a bystander effect through the activation of an antitumor immunity process involving the cGAS/STING pathway." (PMID 38482021, 2024). "Further research is needed to fully understand and optimize the therapeutic potential of combining radiotherapy with cGAS-STING pathway modulation for cancer treatment." (PMID 39834588, 2024). "So, the cGAS-STING pathway provides a new opportunity for pharmacological intervention against cancers." (PMID 38993569, 2024). "The application of cGAS–STING agonists in cancer model mice and clinical treatments has been described in a previous article." (PMID 38525112, 2024). "The development of cancer vaccines targeting the cGAS-STING-IFN I signaling pathway represents another direction in drug development." (PMID 38512518, 2024). "Elevated levels of cytosolic DNA, which can arise from mitotic stress in cancers, radiation therapy, cellular senescence, autoimmune disorders, or genotoxic stress, can lead to persistent activation of the cGAS–STING pathway." (PMID 39456148, 2024). "The cGAS–STING signaling pathway serves as an intracellular warning system that detects the presence of viral DNA or chromosomal DNA from cancer cells within the cytoplasm." (PMID 39518096, 2024).
cancer (continued). "Cancer-intrinsic cGAS-STING activation can be initiated by several mechanisms, such as the loss of DNA repair factors or chromatin fragments resulting from chromosome instability, both of which can generate cytoplasmic dsDNA." (PMID 39449023, 2024). "While cGAS’s influence on cancer development is not fully understood, it presents an interesting biomarker for study in response to immune based cancer therapies." (PMID 38473384, 2024). "Nonetheless, the selective activation of the cGAS-STING pathway and the stimulation of cancer-cell-intrinsic immunity by POLE mutations provide a theoretical-foundations for accurate molecular typing and personalized therapy of malignant tumors." (PMID 38238314, 2024). "TREX1 (Three prime repair exonuclease 1) acts as an innate immune checkpoint, particularly affecting the cGAS-STING pathway which is critical in the immune response against cancer." (PMID 38881902, 2024). "In this review, we focus on the molecular mechanism of photothermal, photodynamic and sonodynamic cancer therapies and the connected role of cGAS-STING agonists in treating cancer." (PMID 39125107, 2024). "Radiotherapy, chemotherapy, and other targeted therapies are commonly utilized in clinical cancer treatments to elicit an antitumor immune response because of their ability to activate the cGAS–STING pathway by producing DNA damage." (PMID 38630271, 2024). "PARPi have been shown to have immunostimulating mechanisms, including activation of the cGAS/STING pathway in cancer cells." (PMID 38993641, 2024). "Therapy‐induced DNA damage is a crucial source of cytosolic dsDNA in cancer cells, which activates the cGAS‐STING pathway." (PMID 38145335, 2024). "Studies have found that these genes are significantly upregulated in nearly all cancer models, indicating a possible universal activation of cGAS-STING signaling in various cancer types." (PMID 38545114, 2024). "Increasing attention has been given to the immunomodulatory potential of TCM, particularly the ability of TCM active compounds or formulations to address diseases such as inflammation, infection, and cancer, by modulating the cGAS-STING signaling pathway." (PMID 39737190, 2024). "It has been reported that the cGAS-STING pathway is often suppressed in lung adenocarcinoma, colorectal cancer, melanoma, liver cancer, gastric cancer, and telomerase-deficient cancer cells." (PMID 40018367, 2024). "The chronic activation of the cGAS-STING pathway in cancers exhibiting rampant chromosome instability is further compounded by DNA damage induced by radiation therapy, chemotherapeutic agents, and mitochondrial DNA leakage due to oxidative stress." (PMID 39450170, 2024). "Recent advancements in cancer research have increasingly focused on the cGAS-STING signaling pathway and its role in tumor progression." (PMID 38545114, 2024). "Recent work also indicates roles for cGAS/STING signaling in the neoplastic compartment in dictating both cancer cell fitness and immune surveillance." (PMID 38226619, 2024). "It is important to recognize that cancer cells can circumvent cGAS-STING signaling and the subsequent immune response through a number of mechanisms." (PMID 38659582, 2024). "Those cancer cell lines expressing all relevant factors supporting the cGAS-STING pathway secreted IFNλ following STING activation whereas only few of them expressed IFNβ." (PMID 40012911, 2024). "It will also be critical to investigate the role of these negative regulatory NLRs in different cancers where cGAS/STING signaling is dysregulated to contribute to tumor growth and metastasis." (PMID 38339107, 2024). "Recently, it was demonstrated that genomic or chromosomal instability in cancer cells results in activation of the innate immune response, mediated by the cGAS-STING-TBK1 pathway, which subsequently leads to JAK/STAT signaling." (PMID 38167507, 2024).
cancer (continued). "Previous studies indicated the activation of cGAS-STING pathway contributed to cancer suppression by promoting host immuno-surveillance and inducing cellular senescence." (PMID 38510490, 2024). "This post-translational modification represents a key regulatory node influencing cGAS-dependent processes in cancer cells." (PMID 39080411, 2024). "Using NanoString gene expression technology, we analyzed tumors from mice treated with the VPS34 inhibitor SB02024 and demonstrated that the expression of CCL5 and CXCL10 is increased through a cGAS-STING-dependent mechanism within cancer cells." (PMID 40395527, 2024). "Previous studies have highlighted the involvement of the NF-κB and cGAS/STING pathways in cancer-related MHC-I expression." (PMID 39106105, 2024). "cGAS/STING activation is essential for efficient cancer therapy including chemotherapy and anti-PD-1/PD-L1 therapies." (PMID 39469633, 2024). "While many inhibitors are aimed at reducing inflammation, cGAS-STING pathway activation has also shown potential in cancer immunotherapy, where stimulating immune responses against tumors is beneficial." (PMID 39669992, 2024). "In mouse models, persistent cGAS activation in cancer cells, followed by paracrine cGAMP uptake by neighboring NK cells, enhances IFN-I signaling and antitumor immunity." (PMID 39450170, 2024). "cGAS localizes in mitochondrial membrane to form oligomerization with dynamin-related protein 1 to inhibit ferroptosis, indicating the potential role of cGAS in regulating ferroptosis and novel targets for cancer." (PMID 39183465, 2024). "Simultaneously, REV activated the cGAS-STING pathway in cancer cells and SR780Fe released Fe3+, which was reduced to Fe2+ by GSH." (PMID 39033108, 2024). "Concomitantly, MSC‐DC no longer induced IFNβ accumulation, or increased HLA‐I expression and NK resistance in cGAS−/− cancer cells." (PMID 38638003, 2024). "On one hand, inactivation of cGAS‐STING signaling reduced the production of type I interferon from endocrine‐resistant cancer cells." (PMID 39023171, 2024). "In vitro experiments showed that combining VPS34 inhibitors with the STING agonist ADU-S100 significantly enhanced the release of proinflammatory cytokines in various cancer cell types in a cGAS-STING-dependent manner." (PMID 40395527, 2024). "Osteocytes inhibit cancer bone metastasis by transferring mitochondria to cancer cells, which induces cGAS/STING‐mediated anti‐tumour immunity." (PMID 39700051, 2024). "Recent research has further illuminated the cGAS-STING pathway’s role in cancer biology, proposing mechanisms for its anti-tumor effects." (PMID 39669992, 2024). "Bloom individuals present high SCEs, increased MN, a self-DNA cGAS-STING-mediated IFN over-expression, and often succumb to cancer before age 30 due to a coincident 10-fold increased mutation rate." (PMID 39669124, 2024). "Emerging research highlights the cGAS/STING pathway as a key immunomodulatory signal in various cancers." (PMID 39403376, 2024). "The anti-cancer effects resulting from inhibition of the cGAS-STING pathway have garnered increasing attention in recent research." (PMID 38817608, 2024). "To address this challenge, we are developing a strategy based on stimulating cancer-endogenous cGAS." (PMID 38413714, 2024). "Previous studies have also shown that senescent malignant cells can induce chronic senescent inflammation, promoting cancer progression by modulation of cytoplasmic chromatin-cGAS-STING pathway." (PMID 38972884, 2024). "Here, we will focus on the role of cGAS/STING activation in cancers with high genomic instability, including tumors with DNA repair defects and tumors displaying CIN/aneuploidy." (PMID 39544936, 2024). "Further in vitro and in vivo studies have demonstrated that cancer-cell intrinsic cGAS activation and subsequent type I IFN expression is necessary for optimal CD8+ T cell priming." (PMID 39544936, 2024).
cancer (continued). "Recent studies suggest that chromosomal instability and aneuploidy and cyclic GMP-AMP synthase (cGAS) can act as biomarkers for cancer severity and patient outcome." (PMID 38473384, 2024). "Previously, it was reported that cGAS-STING signaling cascade affected macrophages polarization in cancer, autoimmune and inflammatory diseases." (PMID 39537618, 2024). "Cancer cells expressing cGAS poses the ability to recognize cytoplasmic DNA and generate cGAMP, which in turn stimulates the secretion of IFN-β and tumor necrosis factor alpha (TNF-α) through the STING pathway." (PMID 38817608, 2024). "It has been detected that the activation of cGAS-STING is often impaired by epigenetic hypermethylation in a variety of cancers." (PMID 39403369, 2024). "Following DC with MSCs, cGAS−/− cancer cells induced a much lower cGAMP level in MSCs than the WT control cells and failed to activate the STING pathway in MSCs." (PMID 38638003, 2024). "According to pan-cancer analysis, a subset of tumors (up to 25%) downregulates the STING pathway through epigenetic silencing of genes encoding STING or cGAS." (PMID 38900577, 2024). "On PRMT9 KD, cancer cells accumulate cytosolic dsDNA, providing abundant substrate for cGAS catalysis." (PMID 38413714, 2024). "Accordingly, it has been shown that cancer cell intrinsic expression of cGAS is critical for cancer immune surveillance since cGAMP produced by cancer cells is transferred to surrounding DCs and promotes type I IFN production in a STING dependent fashion." (PMID 38561826, 2024). "An independent and potentially powerful anti-cancer effect of PP2A/PP5 inhibition stems from the finding that LB-100 also enhances the efficacy of immune checkpoint blockade in different cancer models by fostering T-cell and cGAS-STING activation." (PMID 38600345, 2024). "Epigenetic suppression of cGAS in cancer cells curtails the innate immune response to cytoplasmic DNA accumulation, fostering immune evasion." (PMID 38817608, 2024). "At least some of the effects of CIN on cancer immune evasion appear to involve cGAS/STING signaling, which re-wires the immune landscape towards one that is pro-metastatic." (PMID 39345336, 2024). "Activation of the cGAS-STING pathway plays a key role in the innate immune response to cancer through Type-1 Interferon (IFN) production and T cell priming." (PMID 39178223, 2024). "Emerging evidence suggests that cancer cell-derived DNA can enter the cytosol of DCs and enhance the cGAS-STING-dependent IFN-I response, leading to DC maturation and potent antitumor immune responses." (PMID 39449023, 2024). "Due to its strong immune-stimulatory properties, the cGAS–STING pathway is considered a promising target for cancer immunotherapy." (PMID 39247199, 2024). "STING agonists can directly elicit cancer cell death, and chemotherapeutics can stimulate the cGAS/STING pathway." (PMID 39295301, 2024). "Meanwhile, Lv et al46 found that the tumor suppressor gene TET2 in hepatocellular carcinoma upregulates cGAS expression in cancer cells, activating STING in endothelial cells." (PMID 39834588, 2024). "The status of cGAS-STING activation in patients with ccRCC also needs to be confirmed in human patients with cancer." (PMID 39050705, 2024). "For instance, cGAS/STING was shown to contribute to increased cancer cell survival through autocrine IL-6/STAT3 signaling in cells with induced CIN phenotypes." (PMID 39544936, 2024). "Numerous studies conducted since the discovery of cGAS have revealed a tight relationship between cancer immunotherapy and the cGAS-STING pathway." (PMID 38512518, 2024). "The cytosolic DNA sensing cyclic GMP-AMP synthase (cGAS)-stimulator of interferon genes (STING) pathway represents a promising target for cancer immunotherapy." (PMID 39204392, 2024). "Subsequently, this can be detected by cGAS leading to activation of cGAS/STING signaling pathway in cancer cells." (PMID 38587186, 2024).
cancer (continued). "Is the localization of cGAS in the ‘chromatin bridges’ related to the nucleo-cytoplasmic localization, and is it closely related to the occurrence and development of cancer?" (PMID 38515746, 2024). "With growing acknowledgment of its importance, the cGAS-STING pathway is coming to the forefront as a critical focal point for anti-cancer therapies." (PMID 39170700, 2024). "Activation of the cGAS/STING pathway stokes antitumor immunity by sensing cytosolic double-stranded DNA (dsDNA) from engulfed cancer cells, dsDNA released from nuclear and/or mitochondrial damage, and/or damaged dsDNA in cytosolic micronuclei." (PMID 39621308, 2024). "We also observed that T-DXd-induced HLA-DR expression in DCs was inhibited by anti-IFN-I antibodies, indicating that the cGAS-STING pathway in cancer cells indirectly drives DC activation through IFN-I." (PMID 39449023, 2024). "We look forward to future works clarifying the complex interplay of cGAS-STING signaling in cancer cells and their microenvironment, and the immense potential for combining STING agonists with radiation therapy." (PMID 38659582, 2024). "The synergistic potential of combining the cGAS-STING signaling pathway with ICI therapy in the treatment of malignant tumors presents a promising avenue for clinical translation." (PMID 38817608, 2024). "Our results also showed that BRCA1-mutant cancers exhibited higher cGAS-STING scores and higher pSTAT1 expression." (PMID 38167507, 2024). "Combining photothermal, photodynamic and sonodynamic therapies with cGAS-STING agonists represents a newly developed cancer treatment demonstrating noticeable innovation in its impact on the immune system." (PMID 39125107, 2024). "Subsequently, this promotes the activation of the cytosolic DNA sensing cyclic GMP-AMP synthase/stimulator of interferon genes (cGAS/STING) signaling pathway in cancer cells." (PMID 38587186, 2024). "The cGAS/STING pathway has gained significant attention in cancer research due to its role in the immune response against cancer cells." (PMID 38675916, 2024). "A few recent studies suggest that cancer cells can evade the cGAS-STING pathway simply by suppressing STING expression or by abrogating signals downstream the pathway." (PMID 40012911, 2024). "These cGAS–STING pathway functions explain why cancer patients with low cGAS expression exhibit poor prognoses." (PMID 39161800, 2024). "The cGAS‐STING pathway is involved in different parts of the cancer‐immunity cycle to promote or suppress antitumor immune responses." (PMID 38638003, 2024). "We showed that VPS34 inhibitors increased the secretion of T‐cell‐recruitment chemokines in a cyclic GMP‐AMP synthase (cGAS)/stimulator of interferon genes protein (STING)‐dependent manner in cancer cells." (PMID 38506049, 2024). "At higher radiation doses (12 Gy and 18 Gy), TREX1 is sufficient to scavenge cytoplasmic dsDNA accumulated in some cancer cells, thus preventing excessive activation of the cGAS-STING pathway and inhibiting the downstream interferon (IFN-I) responses." (PMID 39736508, 2024). "In agreement with our finding, the activation of cGAS-STING pathway promotes cytotoxic T cell-mediated cancer cell killing by increasing MHC I molecule expression on the surface of cancer cells." (PMID 38773213, 2024). "STING inhibition provides another way for cancer cells to escape activation of the cGAS–STING signaling pathway." (PMID 38525112, 2024). "Previous studies demonstrated that radiotherapy and certain chemotherapeutic drugs induce cytotoxicity in cancer cells, releasing DNA fragments that activate cGAS-STING, prompting IFN-1 production and immune responses." (PMID 39061208, 2024).